LCP2 (lymphocyte cytosolic protein 2)
Diseases named in the same sentence as LCP2 in open-access papers:
LCP2 is named in the same sentence as 64 diseases in open-access papers, as found by Europe PMC text mining. Sharing a sentence is not in itself a finding about the gene and the disease. The quoted sentences say what the papers report.
atherosclerosis (5 papers, 2019 to 2024). A disease characterized by the build-up of fatty material and calcium deposition in the arterial wall resulting in partial or complete occlusion of the arterial lumen. "These six hub genes, TYROBP, ITGAM, ITGB2, CD86, PLEK, LCP2 may be important biomarkers for the progression of atherosclerosis and potential treatment targets." (PMID 38382092, 2024). "LCP2, EIF4EBP1, HCK, and PPP4C were demonstrated to be highly expressed, and SYNJ2 was demonstrated to be lowly expressed in atherosclerosis compared to the control group, which can be diagnostic biomarkers for patients with atherosclerosis." (PMID 35845072, 2022). "LCP2, EIF4EBP1, HCK, and PPP4C were demonstrated to be highly expressed and SYNJ2 was demonstrated to be lowly expressed in the atherosclerosis mice model." (PMID 35845072, 2022).
COVID-19 (4 papers, 2021 to 2024). A disease caused by infection with severe acute respiratory syndrome coronavirus 2. "PLEK and LCP2 genes which code proteins, pleckstrin and lymphocyte cytosolic protein 2, respectively, may play a role in COVID-19 pathogenesis." (PMID 36510222, 2022). "Seven common key genes were found in these four hub gene sets, including FCER1G, ITGAM, LCP2, LILRB2, MNDA, SPI1, and TYROBP, which were considered core targets of IC and COVID-19." (PMID 38267482, 2024).
Immunodeficiency (4 papers, 2021 to 2024). Failure of the immune system to protect the body adequately from infection, due to the absence or insufficiency of some component process or substance. "On the other hand, PAK2 interacting partners such as ARHGEF7, also known as PAK3 (a positive regulator of apoptosis) and Lymphocyte cytosolic protein 2 (LCP2), have been previously linked to human immunodeficiency." (PMID 35783297, 2022).
colon cancer (3 papers, 2017 to 2021). "A putative molecular network study showed that ARHGAP25 and LCP2 targeted more than five DEGs to play more important roles in colon cancer metastasis." (PMID 34856991, 2021). "This is the first evidence supporting a role for PTPRC, APBB1IP, LCP2, miR-30a-3p, and miR-30e-3p in colon cancer metastasis." (PMID 28629469, 2017). "Therefore, APBB1IP, LCP2, and PTPRC might also play a role in colon cancer metastasis." (PMID 28629469, 2017).
diffuse large B-cell lymphoma (3 papers, 2021 to 2023). "High LCP2 expression is associated with a better prognosis in patients with diffuse large B cell lymphoma." (PMID 34852825, 2021). "Furthermore, LCP2 was overexpressed in lung adenocarcinoma, diffuse large B-cell lymphoma, and melanoma, and it was associated with poor prognosis." (PMID 35734437, 2022).
breast carcinoma (2 papers, 2020 to 2024). "Therefore, it can be concluded that the methylationlevel of the RANBP3 gene is related to HRexpression in breast cancer, and the methylation levelof the LCP2 gene is associated with the degree oftumour malignancy." (PMID 39139156, 2024). "In conclusion, our study highlights alterations inthe methylation patterns of RANBP2, LCP2, andGRAP2 genes in breast cancer tissue, aligning withconsistent changes in methylation levels in bloodcfDNA." (PMID 39139156, 2024). "LCP2 expression was elevated in breast cancer compared with normal breast tissues in three datasets." (PMID 33042828, 2020). "Notably, RANBP3 showed a tendency towards lower methylation in HR+ breast cancer, and LCP2 methylation was correlated with tumour malignancy." (PMID 39139156, 2024). "Our findings propose that the genes RANBP3, LCP2, and GRAP2, located at the identified methylation sites, hold significant potential as molecular markers in blood for the supplementary diagnosis of breast cancer." (PMID 39139156, 2024). "The transcriptional levels of GZMB, LCP2, and SELL were significantly upregulated, whereas GIMAP7 was significantly downregulated, in breast cancer compared with normal breast tissue." (PMID 33042828, 2020). "Subsequently, we investigated the methylation status of the genes Ran-binding protein 3 (RANBP3), Lymphocyte cytoplasmic protein 2 (LCP2), and GRB2 related adaptor protein 2 (GRAP2), situated at the specified sites, using cancer and canceradjacent tissues from 17 breast cancer patients." (PMID 39139156, 2024).
chronic lymphocytic leukemia (2 papers, 2020 to 2021). "High LCP2 protein expression is correlated with aggressive behavior in chronic lymphocytic leukemia cells." (PMID 33911146, 2021). "LCP2 acts as a substrate to activate the T cell antigen receptor signaling pathway and is expressed in chronic lymphocytic leukemia cells." (PMID 33042828, 2020).
melanoma (2 papers, 2021 to 2022). A malignant, usually aggressive tumor composed of atypical, neoplastic melanocytes. "In the present study, we analyzed RNA-seq data by using multiple tools and performed immunohistochemistry of tissue microarray to investigate the expression of LCP2 in melanoma." (PMID 33911146, 2021). "Altogether our results established a novel role of LCP2 as an immune regulator in melanoma and identified LCP2 as a rational prognostic biomarker in patients with metastatic skin cutaneous melanoma receiving anti-PD-1 immunotherapy." (PMID 33911146, 2021). "In conclusion, our results integrated both the expression and function of LCP2 in melanoma using multiple tools, shedding light on the potential role of LCP2 in melanoma, and suggesting LCP2 serves as a prognostic biomarker and therapeutic target in anti-tumor immunity." (PMID 33911146, 2021).
metastatic melanoma (2 papers, 2021 to 2023). A melanoma that has spread from its primary site to another anatomic site. "Quantitative analysis of immunohistochemistry indicated that LCP2 protein was also highly expressed in metastatic melanoma tissue compared to normal skin and primary skin cutaneous melanoma." (PMID 33911146, 2021). "Based on two metastatic melanoma datasets (GSE5446715 and GSE6590416), the prognostic value of LCP2 expression was consistent with the result from the SKCM-Metastasis cohort." (PMID 33911146, 2021).
ovarian carcinoma (2 papers, 2021 to 2022). A malignant neoplasm originating from the surface ovarian epithelium. "LCP2 is associated with hsa-miR-142 expression in ovarian cancer, and hsa-miR-142-related signaling may lead to progressive loss of cell-cell adhesion." (PMID 35360863, 2022). "For instance, LCP2 expression was linked with improved survival in breast and ovarian cancer." (PMID 34834481, 2021). "Through further analysis of these key genes and cancer stem cell subpopulation, more critical genes can be obtained as LCP2, FCGR3A, COL1A1, COL1A2, MT-CYB, CCT5, and PAPPA, are closely associated with ovarian cancer." (PMID 35360863, 2022). "In our new analytical process, the key genes related to ovarian cancer are identified as LCP2, FCGR3A, COL1A1, COL1A2, MT-CYB, CCT5, and PAPPA, which may have important significance in ovarian cancaer and drug therapy." (PMID 35360863, 2022). "Through the analysis of stemness-related key genes and tumor stem cell subpopulations, LCP2, FCGR3A, COL1A1, COL1A2, MT-CYB, CCT5, and PAPPA are closely related to ovarian cancer." (PMID 35360863, 2022).
anaplastic thyroid carcinoma (1 paper, 2024). "A significant over expression of FCGR3A and LCP2 is found in anaplastic thyroid carcinoma (ATC)." (PMID 38568917, 2024).
Chronic colitis (1 paper, 2021). A chronic inflammatory disease of the large intestine (colon, cecum and rectum). "In the current study, the binding of p-STAT1 to the enhancers of TNFAIP2 and LCP2 was significantly increased in tissues from mice with chronic colitis, suggesting that both p-STAT1 deposition and H3K27ac enrichment occur on the same enhancer of both the TNFAIP2 and LCP2 genes." (PMID 34112215, 2021).
colitis (1 paper, 2021). Inflammation of the colon. "We verified by ChIP-PCR that H3K27ac enrichment was increased at the enhancers of LCP2 and TNFAIP2 in mice with DSS-induced colitis." (PMID 34112215, 2021). "We found that p-STAT1 binds to EP300 to regulate the expression of LCP2 and TNFAIP2 by promoting H3K27 acetylation at enhancers, and thus, we further investigated whether the increase in H3K27ac levels mediated by EP300 is involved in the development of colitis in mice." (PMID 34112215, 2021).
diabetes (1 paper, 2023). "Drugs closely related to diabetes, such as Fenretinide, Dimethylamine parthenolide, Chelerythrine, etc., have obvious positive correlation with LCP2, TYROBP, RPL3, CDK4, and CD44." (PMID 36755923, 2023). "First, we selected the central core sites in the PPI network of AS, DN, DR and found six characteristic genes of diabetes (TYROBP, LCP2, CCL2, CD44, RPL3, CDK4)." (PMID 36755923, 2023).
ductal breast carcinoma in situ (1 paper, 2020). A carcinoma entirely confined to the mammary ducts. "Similarly, LCP2 was significantly upregulated in ductal breast carcinoma in situ in the Ma dataset." (PMID 33042828, 2020).
escherichia coli infection (1 paper, 2024). Infection with the organism Escherichia Coli. "Few targeted genes in humans like LCP2, GABRA6, and MYH14 were predicted to be associated with disease pathways of Yesinia infection (hsa05135), neuroactive ligand-receptor interaction (hsa04080), and pathogenic Escherichia coli infection (hsa05130), respectively." (PMID 38674383, 2024).
invasive ductal breast carcinoma (1 paper, 2020). The most common type of invasive breast carcinoma, accounting for approximately 70% of breast carcinomas. "The transcriptional level of LCP2 was higher in invasive ductal breast carcinoma than normal breast tissues in the Karnoub dataset (p = 2.52e-6) and the Zhao dataset (p = 3.82e-5)." (PMID 33042828, 2020).
liver carcinoma (1 paper, 2024). An epithelial or non-epithelial malignant neoplasm that arises from the liver. "Three genes, namely, CLEC4G, LCP2, ST8SIA1 are acting as biomarkers in liver carcinoma." (PMID 38674383, 2024).
lung carcinoma (1 paper, 2022). "LCP2 is also a good prognostic biomarker for lung cancer patients." (PMID 36744181, 2022).
Obesity (1 paper, 2023). Accumulation of substantial excess body fat. "The hub genes calculated by Cytoscape software are MNDA (score 320), CYBB (score 314), CD86 (score 312), FCGR2C (score 242), NCF2 (score 240), LCP2 (score 182), TLR8 (score 148), HLA-DRA (score 54), LCP1 (score 30), and PTPN22 (score 8), which are considered to be associated with obesity-related AF." (PMID 36671813, 2023).
parasitemia (1 paper, 2012). "LCP3 also conferred a significant reduction in liver-stage parasite burden and blood-stage parasitemia; whereas LCP1 and LCP2 conferred protection against liver-stage parasite burden only." (PMID 22936972, 2012).
prostate carcinoma (1 paper, 2019). A carcinoma that arises from epithelial cells of the prostate gland. "TIMER was used for correlation analysis and it indicated that UBASH3B was significantly correlated with LCP2 (p = 3.37e-40, cor = 0.547), PIK3CG (p = 2.44e-38, cor = 0.536), and BIRC3 (p = 0, cor = 0.534) in prostate cancer." (PMID 32010618, 2019). "Moreover, LCP2, PIK3CG, and BIRC3 were also positively correlated with these six types of immune cells in prostate cancer." (PMID 32010618, 2019).
psoriasis (1 paper, 2015). An autoimmune condition characterized by red, well-delineated plaques with silvery scales that are usually on the extensor surfaces and scalp. "Immune-related genes (e.g. CCL8, LCP2, CD1E) and IL-36G, which was recently associated with psoriasis pathogenesis, were increased in AD LS skin." (PMID 26459294, 2015).
skin cutaneous melanoma (1 paper, 2021). "LCP2 expression in metastatic skin cutaneous melanoma (SKCM-Metastasis) was higher than primary skin cutaneous melanoma (SKCM-Primary)." (PMID 33911146, 2021).
thrombosis (1 paper, 2019).
type 1 diabetes (1 paper, 2007). "(III) Markers related to diseases other than cancer include WASF2, LCP2 and FYB (Wiscott-Aldrich syndrome, all up) and TAP2 (up, polymorphisms in this gene are implicated in type 1 diabetes." (PMID 19455236, 2007).
Yersinia infection (1 paper, 2024). "For example, the targeted gene LCP2 is involved in eight pathways including important pathways like, Rap1 signaling pathway, osteoclast differentiation, Yersinia infection, platelet activation, T-cell receptor signaling pathway, and Fc epsilon RI signaling pathway." (PMID 38674383, 2024).
tumor (25 papers, 2015 to 2025). "LCP2 expression was correlated with tumor-infiltrating B cell, CD8+ T cell, CD4+ T cell, macrophage, neutrophil and dendritic cell in SKCM-Metastasis cohorts." (PMID 33911146, 2021). "Elevated expression level of FYN (p value = 0.000), LCP2 (p value = 0.002), PTPRC (p value = 0.011), WAS (p value = 0.005), ZAP70 (p values = 0.000) and NCF4 (p values = 0.047) were associated with tumor size." (PMID 34834481, 2021). "Specifically, in the tumor from patient #7, genes involved in T cell activation and signaling such as PTPRC (which encodes CD45), LCP2, FYB, CD3E, and LCK, and in genes involved in immune response and interferon signaling such as STAT1, OAS2, and HLA were downregulated." (PMID 37620318, 2023). "The function of LCP2 might vary from diseases, and further studies are required according to the gene profile alteration of immune cells in the tumor microenvironment." (PMID 33911146, 2021). "Additionally, we performed correlation analysis to corroborate the relationship between tumor infiltrated immune cells and the expression of the seven key hub genes (CTLA4, PRF1, LCK, CD3E, CD247, ZAP70, and LCP2) in ARID1A-PIK3CA mutational co-occurrence tumors." (PMID 38017109, 2023). "For validation, qRT-PCR of an ESCC patient cDNA microarray was performed, and demonstrated that C1QA, C3AR1, LCP2, SPI1, and TYROBP were up-regulated in tumor samples and predict poor prognosis." (PMID 34926275, 2021). "In this study, using RNA-seq data of 576 HCC patients, a panel of seven genes (including LCP2, TYROBP, ZAP70, PTPRC, FYN, WAS and NCF4) has been identified which are independent predictors of delayed tumor recurrence and improved patient prognosis." (PMID 34834481, 2021). "LCP2 protein plays an important role in the TCR-mediated signal transduction pathway and tumor malignancy." (PMID 33911146, 2021). "Therefore, these four tumor antigens (NLCR4, LCP2, TMEM229B, FCRL4) were considered as potential candidates for ESCC mRNA vaccine with immune activation and can be processed and presented by APCs to induce an immune response." (PMID 35734437, 2022). "Additionally, the analysis showed that C1QA, C3AR1, LCP2, SPI1, and TYROBP were up-regulated in tumours with the worst prognosis." (PMID 35743646, 2022). "Our previous study indicated that lymphocyte cytosolic protein 2 (LCP2) protein tightly interacted with UBASH3B protein, which was identified as a novel prognostic biomarker and correlated with immune cell infiltration in the tumor microenvironment." (PMID 33911146, 2021). "In addition, LCP2 protein tightly interacted with UBASH3B protein, which was identified as a novel prognostic biomarker and correlated with immune cell infiltration in the tumor microenvironment." (PMID 33911146, 2021). "Similarly, the expression of BTN3A1, CSF2RB, GIMAP7, GZMB, HCLS1, LCP2, and SELL was positively correlated with the infiltration of B cells, CD8+ T cells, CD4+ T cells, neutrophil, and DCs, but was negatively correlated with the tumor purity." (PMID 33042828, 2020).
cancer (12 papers, 2007 to 2025). A tumor composed of atypical neoplastic, often pleomorphic cells that invade other tissues. "Thus, changes in LCP2 gene methylationserve as a potential marker for cancer occurrence andoffer diagnostic efficiency of 83.9%." (PMID 39139156, 2024). "LCP2 is involved in T cell activation and can increase the IL-2 gene promoter activity following transient overexpression, which is associated with better prognosis of cancer patients." (PMID 37500893, 2023). "Among them, seven genes (FHL1, SELL, VIM, IGFBP7, TNFAIP3, LCP2, and SLC7AB) were associated with the cancer-immunity cycle." (PMID 35565437, 2022). "To explore the expression of LCP2 in malignant tumors, we first investigated the Oncomine database, which contains abundant microarray data of GEO and TCGA database." (PMID 33911146, 2021). "In comparison with corresponding normal tissues, LCP2 was upregulated in 7 types of cancers, while downregulated in 5 types of cancers." (PMID 33911146, 2021). "In comparison with normal tissue, there were 25 studies showing that LCP2 was upregulated in cancer, whereas 10 studies reporting downregulated LCP2 in cancer." (PMID 33911146, 2021). "Additionally, it is the initialinvestigation to validate the association betweenRANBP2, LCP2, and GRAP2 gene methylation andbreast cancer." (PMID 39139156, 2024). "Our analysis revealed that RANBP3, LCP2, and GRAP2 genes exhibited significant methylation differences between cancer and cancer-adjacent tissues." (PMID 39139156, 2024). "A ROC curve showed that when the sensitivitywas 86.67% (RANBP3), 82.35% (LCP2) and88.24% (GRAP2), the specificity of breast cancerdiagnosis was 93.3%; the sensitivity of identifyingbreast cancer patients by the comprehensive methylationlevel of the three genes was 94.1%, with aspecificity of 93.3%." (PMID 39139156, 2024). "Furthermore, our researches have found two important intersection proteins, LCP2 and LAIR1, which possibly had potential prognostic value or serve as immunotherapeutic targets for cancers." (PMID 39367146, 2024).
infection (3 papers, 2009 to 2016). The state of being infected such as from the introduction of a foreign agent such as serum, vaccine, antigenic substance or organism. "In addition, the LCP2 gene showed significant increased expression in macrophages upon infection with 2D6 mutant, in contrast to wild-type infected macrophages." (PMID 20359357, 2010). "Moreover, it is also interesting to note that a few genes such as SERPINE1 and LCP2 respond differently in the two tissues studied, and while some of the pathways responding to the infection are ubiquitous, others appear to be tissue specific." (PMID 19948073, 2009).
LCP2 also shares sentences with these, for which no sentence is quoted: acute kidney injury (1 paper); allergic asthma (1); allergies (1); atrial fibrillation (1); autoimmune disease (1); B cell lymphoma (1); bladder tumor (1); breast tumors (1); cardiovascular diseases (1); cholestasis (1); clear cell renal cell carcinoma (1); gastric cancer (1); glioblastoma (1); Granuloma (1); hemorrhage (1); HIV-1 infection (1); immunodeficiency 81 (1); inflammatory bowel disease (1); influenza (1); ischemic cardiomyopathy (1); ischemic stroke (1); leukemia (1); lung adenocarcinoma (1); lymph node metastasis (1); lymphedema (1); lymphoma (1); metabolic disease (1); Opportunistic infection (1); preeclampsia (1); pulpitis (1).
A further 4 diseases each share a sentence with LCP2 in 1 paper.